H19 (H19 imprinted maternally expressed transcript)
Diseases named in the same sentence as H19 in open-access papers (continued):
Sharing a sentence is not in itself a finding about the gene and the disease.
liver cancer (continued). "Regarding chemosensitivity, liver cancer cells stably overexpressing H19, established by plasmid transfection, were treated with doxorubicin or sorafenib." (PMID 32429417, 2020). "Although the function of H19 in HCC remains elusive, a short outlook summarizes some ideas of using the H19 locus as a novel target for liver cancer therapy." (PMID 32429417, 2020). "The study determined the role of H19 in three different human liver cancer cell lines (HepG2, Plc/Prf5, and Huh7) resistant to either doxorubicin or sorafenib." (PMID 32429417, 2020). "Supporting the role of H19 as an oncogene, H19 was shown to be upregulated in the liver cancer cell line Hep3B as a response to hypoxic stress." (PMID 32429417, 2020). "The lncRNA CUDR accelerates liver cancer stem cell growth by binding cyclinD1 and, as a complex, binding both the promoters of H19 and c-Myc." (PMID 28933364, 2017). "Due to the downregulation of H19 in HCC we aimed to determine functional aspects of H19 overexpression in liver cancer cells." (PMID 31225433, 2017). "Examination of changes in phase II glutathione conjugation and in drug transporters after H19 knockdown in liver cancer cell lines should further be explored, as these enzymes are important for clearing drugs and for the accumulation of drugs in cancer cells." (PMID 28933364, 2017). "Pu and colleagues found that H19 together with another lncRNA CUDR promotes liver cancer stem cell growth through upregulating TERT and C-Myc." (PMID 26989025, 2016). "Together, these results suggest CUDR overexpression cyclinD1 overexpression PTEN knockdown synergistically enhances H19 expression in liver cancer stem cells." (PMID 26513297, 2015). "The CUDR and H19 expression were significantly increased in liver cancer stem cell line compared to the liver cancer unstem cell line." (PMID 26513297, 2015). "Researchers on human liver cancer cell lines found that upregulating the expression of lncRNA H19 and miR-675 May block the Akt/GSK-3/Cdc25A signalling pathway." (PMID 39697114, 2025). "In liver cancer, the long non-coding RNA (lncRNA) H19 is a specific target of NSUN2." (PMID 40370440, 2025). "Furthermore, butyrate promotes liver cancer metastasis by increasing the expression of H19 in tumor cells through the inhibition of HDAC2, leading to increased H3K27 acetylation at the H19 promoter and inducing M2 macrophage polarization." (PMID 40299650, 2025). "The lncRNAs of interest for this test—namely ANRIL, H19, HOTAIR, HULC, MALAT1, WISPER, and ZFAS1—were initially identified in other pathologies, as evident in some of their names, highly upregulated in liver cancer (HULC), or metastasis associated lung adenocarcinoma transcript 1 (MALAT1)." (PMID 40271126, 2025). "The validation of this hypothesis will help us understand how sex-differential expression of H19 affects liver cancer outcomes." (PMID 38095719, 2024). "Clusters 1, 2, 3, 5, and 6 represented genes that were highly expressed in stages of embryonic development, but were expressed at low levels in adult livers, including oncofetal genes Afp, Gpc3, Sall4 (cluster 2), H19 (Cluster 3) and Igf2 (Cluster 5), which are re-expressed in liver cancer." (PMID 38225233, 2024). "Many studies have shown that H19 could act as an independent lncRNA to regulate the expression of miR-675, which plays an oncogenic role in liver cancer." (PMID 36960964, 2023). "H19 can affect many critical biological processes, including the cell proliferation, apoptosis, invasion, and metastasis of liver cancer by its function on epigenetic modification, H19/miR-675 axis, miRNAs sponge, drug resistance, and its regulation of downstream pathways." (PMID 36960964, 2023). "Study shows the volume of liver cancer tumors reduces by 82% in animal models of liver cancer when H19 (the first reported lncRNA) is knocked out, which fully confirms the tumorigenic effect of H19." (PMID 34799469, 2021).
liver cancer (continued). "Furthermore, H19 has been shown to have an adverse effect on sorafenib therapy for liver cancer, inhibiting the sensitivity of liver cancer cells to sorafenib via upregulation of miR-675." (PMID 34771525, 2021). "For instance, lncRNA H19 was found to be highly expressed in CD90+ liver cancer cells." (PMID 31448238, 2019). "Moreover, it has been proposed that the functionality of H19 in liver cancer is seemingly much more intricate than that in other types of tumors because of the highly heterogeneous etiology." (PMID 31277475, 2019). "Our previous studies showed that H19 enhanced Pim1 expression and function in the liver cancer." (PMID 27167190, 2016). "As a consequence, H19 may contribute to multidrug resistance in liver cancer cell lines by inducing demethylation of MDR1 promoter and overexpression of P-glycoprotein." (PMID 25861629, 2015). "Higher H19 levels can simply be the result of altered chromatin structure in liver cancer." (PMID 25861629, 2015). "Although increment of H19 may partly contribute to miR675 medicated promotion of liver cancer cell growth, our findings in this study provide novel evidence for an active role of H19 in miR675-mediated promotion of liver cancer cell growth." (PMID 26376677, 2015). "PKM2 determines the miR675 and H19 oncogenic action partly, at least in liver cancer." (PMID 26376677, 2015). "Moreover, H19 is highly expressed in liver cancer cell lines, and hypoxic conditions strongly upregulate H19 levels." (PMID 26064090, 2015). "Although the increment of H19 may partly contribute to CUDR medicated promotion of liver cancer stem cells, liver stem cells growth, our findings in this study provide novel evidence for an active role of H19." (PMID 26513297, 2015). "Given that miR675 activates PKM2 through H19 in liver cancer cell, we should consider whether miR675 oncogenic function depends on activity of PKM2." (PMID 26376677, 2015). "However, further research reveals that in hepatic cancer cells, upregulated H19 functions as a ceRNA by sponging miR-520a-3p, thereby relieving its suppressive effect on LIM domain kinase 1 (LIMK1), an enzyme that promotes HCC cell proliferation, metastasis, and inhibits apoptosis." (PMID 40781643, 2025). "Interestingly, it was also reported that miR-675 could upregulate H19 through activating EGR1 in human liver cancer, suggesting a potential positive feedback loop of H19-miR-675 expression in HCC." (PMID 36960964, 2023). "In addition, microRNA-22 has been found regulated by lncRNA H19 in HBV-related liver cancer." (PMID 34869051, 2021). "We found that a specific haplotype of H19 (CTG) was significantly associated with increased susceptibility to HCC (OR, 1.237; 95% CI, 1.015–1.507; p = 0.035; AOR, 1.240; 95% CI, 1.008–1.526; p = 0.042), further suggesting a genetic predisposition of H19 to liver cancer." (PMID 31277475, 2019). "Recent studies reported that H19 plays a critical role in the progression of HCC and CCA, the two major pathophysiological subtypes of primary liver cancer." (PMID 36960964, 2023). "Some lncRNA, which where found to be significantly increased in other liver cancers, such as HULC (highly upregulated in liver cancer), HOTAIR and HOTTIP only showed a mild increase in FLC; while others, such as H19, showed a decrease." (PMID 29535801, 2018). "Increased expression of H19 promotes excessive TERT enhancing telomerase activity, and c-Myc increases liver cancer stem cell proliferation." (PMID 28933364, 2017). "To this data, we report that the upregulated expression level of miR675, H19, HP1α, EGR1, PKM2, H-Ras were consistent in liver cancer patients and miR-675 upregulates long noncoding RNA H19 through activating EGR1 in human liver cancer cells." (PMID 26376677, 2015).
liver cancer (continued). "The ECR1 of the H19/IGF2 domain is usually methylated in normal tissues, but it becomes hypomethylated in a couple of cancer samples, including lung and liver cancers." (PMID 26338779, 2015). "In addition, some lncRNAs, such as lncRNA H19, are enriched in exosomes released by CD90 + liver cancer cells." (PMID 36793126, 2023). "H19 lncRNA with m5C change specifically binds to G3BP1 protein, further leading to the accumulation of oncoprotein and promoting the occurrence and progression of liver cancer." (PMID 35686101, 2022). "Interestingly, lncRNA H19, which was packed inside exosomes secreted by CD90+ liver cancer cells, was conveyed to and internalized by endothelial cells." (PMID 31448238, 2019). "Our method predicted that ncRNAs H19, PCNA-AS1 and WRAP51 are correlated with liver cancer." (PMID 29671405, 2018). "Our previous study showed that the overexpression of H19 increases the binding of TERT to TERC and reduces the interplay between TERT with TERRA, thus enhancing the cell telomerase activity and extending the telomere length in liver cancer stem cells." (PMID 27167190, 2016). "Although miR675 ‘s oncogenic function was due to decrease the HP1 isoforms and increase H19, PKM2 in liver cancer cells, we further confirm how miR675-HP1-EGR1-H19-PKM2 axis might be played an important role in hepatocarcinogenesis and progression." (PMID 26376677, 2015). "At the first time, our results showed that the expression level of miR675, H19, HP1α, EGR1, PKM2, H-Ras were consistent in 10 cases of liver cancer patients and their upregulated expression rate added up to 100% (liver cancer tissue vs paracancerous liver tissue)." (PMID 26376677, 2015). "However, the expression of hepatic H19 is reactivated under pathological conditions, such as nonalcoholic steatohepatitis, cholestatic liver fibrosis, and liver cancers." (PMID 36960964, 2023). "In addition, hypermethylation and overexpression of lncRNA H19 were identified in liver cancer tissues compared to matched non-cancerous liver tissues, and a higher level of H19 RNA m5C methylation was correlated with HCC progression." (PMID 32978516, 2020). "H19 is a lncRNA that was upregulated in cancer stem cell CD90+ liver cancer cell-derived exosomes, but not in normal liver cancer cell-derived exosomes." (PMID 36905871, 2023). "Although, the direct H19 and EZH2 binding has not been determined in liver, EZH2 has been shown to silence tumor suppressor microRNAs in liver cancer and is upregulated in HCC." (PMID 28933364, 2017). "For the treatment of liver cancer, AP may suppress tumor growth of HCC through the long non-coding RNA H19-mediated Wnt/β-catenin signaling regulatory axis, which indicated that the H19 was a potential therapeutic target for HCC." (PMID 39512816, 2024).
Obesity (51 papers, 2007 to 2026). Accumulation of substantial excess body fat. "The current study provided clues for association between two H19 polymorphisms and obesity in Iranian population." (PMID 37326896, 2024). "In the current study, we aimed to find the association between two possibly functional H19 polymorphisms, namely rs217727 and rs2839698 and obesity in Iranian population." (PMID 37326896, 2024). "In the current study, T allele of this SNP was found to confer risk of obesity which is in line with the role of H19 in obesity and the effect of T allele of this SNP on expression of H19." (PMID 37326896, 2024). "Accordingly, we performed this case-control study with 150 children and adolescents as a pilot investigation into the association between MALAT1 rs3200401 and H19 rs217727, and obesity in children and adolescents aged between 5 and 17 years old." (PMID 37104004, 2023). "We aimed to evaluate the possible associations between the SNPs rs3200401 in MALAT1 and rs217727 in H19, and an individual’s risk of obesity." (PMID 37104004, 2023). "A CeRNA, Inc-H19, contributed to obesity-associated bone loss, acting as a competitive inhibitor binding to complementary MiRNAs, and blocking its actions." (PMID 36831188, 2023). "The preoperative level of lncRNA H19 in VAT can be used to predict excess weight loss in patients with obesity after bariatric surgery." (PMID 35629301, 2022). "In summary, despite the limitations, the current study demonstrated that reduced H19 levels were involved in obesity-induced cardiac dysfunction, and the underlying mechanisms were also elucidated." (PMID 34050133, 2021). "We have proved through in vivo and in vitro experiments that normally processed BMSCs‐derived exosomes can increase the expression of H19 and play a role in the treatment of osteogenic differentiation and poor fracture healing caused by obesity." (PMID 33471953, 2021). "In summary, this study further found that H19 plays an important role in the poor healing of fractures caused by obesity by combining with previous studies." (PMID 33471953, 2021). "To study the specific role of H19 in the pathology underlying insulin resistance, we used db/db mice as our model, which are widely used to study type 2 diabetes and obesity." (PMID 33115498, 2020). "In a high-fat diet model of obesity in mice, insulin resistance in the muscle was associated with a decrease in H19, an increase in let-7, and a decrease in two let-7 targets: the IR and lipoprotein lipase." (PMID 31590432, 2019). "The association among the altered methylation of the H19 imprinting control region and H19/miR-675 expression in obesity-induced cancers remains to be explored." (PMID 30154386, 2018). "In brief, without adjusting for potential confounders we detected significantly lower methylation at the IGF2 DMR associated with paternal obesity, and significantly higher methylation at the H19 DMR when the mother was obese." (PMID 23388414, 2013). "Loss of H19 in brown fat reduces energy expenditure and sensitizes towards obesity." (PMID 39125332, 2024). "Furthermore, mice treated with H19 RNA reportedly resisted HFD- or leptin deficiency-induced obesity." (PMID 36604148, 2022). "H19 expression in SAT and VAT negatively correlates with BMI; however, whether an obesity-associated decline in adipose H19 affects the regulation of skeletal muscle mass remains to be investigated." (PMID 33528828, 2021). "Although these effects of H19 have been reported, to the best of our knowledge, the current study is the first to demonstrate the effects of H19 expression in vivo, especially in cardiomyocytes or H9c2 cells, on obesity-associated cardiac damage." (PMID 34050133, 2021). "Furthermore, IGF2/H19 DMR methylation changes have also been associated with paternal obesity or the risk of overweight, diabetes or some types of cancer in early life." (PMID 31615571, 2019).
Obesity (continued). "H19 gene polymorphism participates in the regulation of lncRNA H19 expression, which has been reported to be associated with the risk factors of ischemic stroke, such as coronary artery disease, obesity, and blood pressure." (PMID 28203482, 2017). "In addition to H19/Igf2 imprinting patterns, other genes that predispose for obesity can be affected by maternal diet." (PMID 17805414, 2007). "Furthermore, alterations in fetal growth related to H19/Igf2 imprinting are associated with metabolic disorders in adulthood, including obesity and diabetes." (PMID 17805414, 2007). "Therefore, H19 has been found to be involved in the obesity-associated conditions." (PMID 37326896, 2024). "Taken together, H19 polymorphisms may affect risk of obesity in Iranian population." (PMID 37326896, 2024). "First, despite the potential effects and underlying mechanisms of H19 in counteracting obesity-induced mitochondrial and cardiac dysfunctions in vivo and in vitro, Parkin-related mitophagy in this situation has already been reported and this part may not be attractive enough." (PMID 34050133, 2021). "One mechanism of how H19 supports EE could be its cell-intrinsic control of mitochondrial biogenesis in mature brown adipocytes and the ensurance of maintaining quiescence of obesity-predisposing PEGs in BAT." (PMID 30190464, 2018). "Mice treated with an H19 gain‐of‐function (GOF) mutant (AGR–H19–Rgof) were resistant to HFD‐ and leptin deficiency‐induced obesity." (PMID 39764565, 2025). "Enhancing H19 expression suppresses excessive mitophagy by restricting the translation of Pink1 mRNA, thereby alleviating obesity-induced cardiomyopathy." (PMID 40004130, 2025). "Among them, IGF2/H19 is involved in the pathogenesis of obesity-related diseases such as diabetes mellitus, and evidence suggested that parental obesity impacts the DNA methylation of IGF2 in offspring." (PMID 40302954, 2024). "The authors found that obesity markedly reduces the expressions of lncRNA H19 in plasma and bone marrow mesenchymal stromal cell (BMSC) exosomes, thereby disrupting osteogenesis and impairing fracture healing." (PMID 39765643, 2024). "Expression levels of H19 have been inversely correlated with obesity indices and homeostasis model assessment of insulin resistance values." (PMID 37326896, 2024). "This includes the widely studied MALAT1 and H19 lncRNAs, previously discovered in other contexts and more recently assigned to obesity-relevant roles." (PMID 37104004, 2023). "The absence of VAT samples in the control group made it impossible to compare VAT lncRNA H19 levels in control subjects and patients with obesity." (PMID 35629301, 2022). "H19 expression had an inverse correlation while MEG3 expression had a positive correlation with obesity indices and HOMA-IR values in humans." (PMID 36555704, 2022). "Differences in the expression of lncRNA H19 in SAT were revealed between patients with obesity and obesity accompanied by ICM." (PMID 35629301, 2022). "Namely, in contrast to patients with obesity accompanied by ICM, patients with obesity have higher levels of SAT lncRNA H19, which decreased in response to bariatric intervention." (PMID 35629301, 2022). "Since adipose tissue from different depots makes different contributions to the pathogenesis of obesity and the characteristics of the response to therapy, it is of interest to assess the levels of lncRNA H19 in SAT and VAT depots as well as in plasma." (PMID 35629301, 2022). "This indicates that ICM has some effect on the expression of lncRNA H19 in SAT of patients with obesity." (PMID 35629301, 2022). "Several studies have found that paternal fast food intake and obesity can lead to changes in DNA methylation and expression of Meg3 and Nnat in sperm, and Igf2/H19 in the offspring." (PMID 36386900, 2022).